PFKFB2 (6-phosphofructo-2-kinase/fructose-2,6-biphosphatase 2)
Diseases named in the same sentence as PFKFB2 in open-access papers (continued):
Sharing a sentence is not in itself a finding about the gene and the disease.
renal fibrosis (2 papers, 2020 to 2023). A final common manifestation of a wide variety of chronic kidney diseases characterized by glomerulosclerosis and tubulointerstitial fibrosis. "This was associated in PFKFB2 KI mice with increased renal fibrosis, which was more severe in the unilaternal ureteric obstruction (UUO) model compared with the folic acid nephropathy (FAN) model." (PMID 32884050, 2020). "To determine the role of glycolysis in renal fibrosis, we generated a transgenic mouse with mutations in the regulatory phosphorylation sites of PFKFB2." (PMID 32884050, 2020). "Overall, this indicated a marginal effect of the PFKFB2 KI mutation on renal fibrosis in the FAN model." (PMID 32884050, 2020). "The reduction in macrophage numbers that has been reported with metformin in models of renal fibrosis was seen in both WT and PFKFB2 KI UUO kidneys and TNF-α as a marker of inflammation was also similarly reduced." (PMID 36757995, 2023). "We were interested to determine its likely distribution in the kidney in renal fibrosis, since this would affect our interpretation of studies performed in the PFKFB2 KI mice." (PMID 32884050, 2020). "To determine the role of regulation of tubular glycolysis by PFKFB2 in the development of renal fibrosis, we developed a transgenic mouse that has inactivating mutations of the regulatory Ser468 and Ser485 phosphosites in PFKFB2." (PMID 32884050, 2020).
atrial fibrillation (1 paper, 2025). A disorder characterized by an electrocardiographic finding of a supraventricular arrhythmia characterized by the replacement of consistent P waves by rapid oscillations or fibrillatory waves that vary in size, shape and timing and are accompanied by an irregular ventricular response. "In the atrial fibrillation dataset, LDHB, PFKFB2, CKAP4, CXCR4, DPEP2, and RORA genes showed an upregulation trend, while only the CD81 gene was downregulated in the disease group." (PMID 41359645, 2025). "In the selection of feature genes for atrial fibrillation, LDHB, DPEP2, BCL11B, CKAP4, RORA, PFKFB2, and CXCR4 were identified as potentially important predictors, with the model error being lowest when the number of genes reached eleven." (PMID 41359645, 2025).
bacterial pneumonia (1 paper, 2025). Acute infection of the lung parenchyma caused by bacteria (e.g., Streptococcus pneumoniae, Haemophilus influenzae, Chlamydia pneumoniae, Mycoplasma pneumoniae, and Legionella pneumophila). "Analyses of lung tissues from patients with PQ poisoning, secondary bacterial pneumonia (2°BP), and Coronavirus Disease 2019 (COVID-19), as well as from normal controls, confirmed these findings, showing increased PFKFB2 expression and DC maturation during ALI." (PMID 40736063, 2025).
bladder cancer (1 paper, 2020). "Moreover, Western blot analysis showed that Vitamin K2 stepwise elevated the expression of some glycolytic proteins or enzymes, such as GLUT-1, Hexokinase II (HK2), PFKFB2, LDHA and PDHK1, in bladder cancer T24 and EJ cells." (PMID 32382009, 2020).
brain glioma (1 paper, 2023). A malignant glioma that involves the brain. "Finally, we performed a rescue test to validate if miR-21-5p was implicated in the glycolysis of brain glioma cells through regulating of PFKFB2." (PMID 37864733, 2023). "The present study selected U251 cells to explore if miR-21-5p was involved in the glycolysis of brain glioma through mediating PFKFB2." (PMID 37864733, 2023). "These indicated miR-21-5p mediated PFKFB2 to diminish the glycolysis of brain glioma cells, thus hindering the brain glioma cell growth and migration (P < 0.001)." (PMID 37864733, 2023). "These indicated that knockdown of PFKFB2 inhibited the glycolysis and then the brain glioma cell growth and migration." (PMID 37864733, 2023). "miR-21-5p level is elevated in brain glioma and can impede brain glioma cell growth via regulating the glycolysis mediated by PFKFB2, thus is a potential target of treating brain glioma." (PMID 37864733, 2023). "This uncovered that miR-21-5p impeded the glycolysis of brain glioma cells through regulating of PFKFB2 and was a potential pathway to treat brain glioma." (PMID 37864733, 2023). "To conclude, miR-21-5p is elevated in brain glioma and can restrain brain glioma cell growth and migration via modulating the glycolysis mediated by PFKFB2, thus is a potential target of treating brain glioma." (PMID 37864733, 2023). "Reduced proliferative cells, invaded cells, and migrated cells were observed in brain glioma cells upon treatment with si-PFKFB2 than that after transfection of si-NC (P < 0.001)." (PMID 37864733, 2023). "We found high expression of PFKFB2 in brain glioma through microarray analysis and validated PFKFB2 was a miR-21-5p target gene, yet whether the same effect existed in brain glioma was unclear." (PMID 37864733, 2023). "This work disclosed that PFKFB2 was modulated by miR-21-5p in brain glioma." (PMID 37864733, 2023). "We examined miR-21-5p and PFKFB2 levels in brain glioma cells via qRT-PCR." (PMID 37864733, 2023). "Moreover, miR-21-inhibit could hinder cell viability, invasion, and glycolysis triggered by overexpression of PFKFB2 in brain glioma cells." (PMID 37864733, 2023).
cardiomyopathy (1 paper, 2025). A disease of the heart muscle or myocardium proper. "PFKFB2 played a crucial role in glycolysis, and its elevated levels in the heart could prevent cardiomyopathy while providing systemic metabolic benefits." (PMID 41019282, 2025).
colorectal cancer (1 paper, 2023). A primary or metastatic malignant neoplasm that affects the colon or rectum. "PFKFB2 has also been reported to have an opposite expression pattern in colorectal cancer, where decreased PFKFB2 was correlated with poor prognosis in patients." (PMID 38201444, 2023).
hepatocellular carcinoma (1 paper, 2017). A malignant tumor that arises from hepatocytes. "Interestingly, high expression of PFKFB2, a hypomethylated gene found in the classifier, was reported as being associated with advanced TNM stage and also was implied in poor overall survival in hepatocellular carcinoma." (PMID 28938489, 2017).
Hypertension (1 paper, 2023). The presence of chronic increased pressure in the systemic arterial system. "A subnetwork with alanine, glutamine, urea cycle (citrulline, arginine), and 1-carboxyethylvaline linked to PFKFB2 and TXNIP revealed associations with kidney function, hypertension and triglyceride metabolism." (PMID 37679740, 2023).
Insulin resistance (1 paper, 2025). Increased resistance towards insulin, that is, diminished effectiveness of insulin in reducing blood glucose levels. "We showed that PFKFB2 is labile and the enzyme is rapidly degraded in the absence of insulin signaling, and thus becomes chronically decreased in a type 1 diabetes model and with insulin resistance." (PMID 40310487, 2025).
Intervertebral disc degeneration (1 paper, 2022). "AC063977.6/miR-338-3p/PFKFB2 may regulate metabolic event during Intervertebral disc degeneration (IDD) pathogenesis." (PMID 35935642, 2022).
Myocardial fibrosis (1 paper, 2022). "PFKFB2 may play a key role in reflecting the transition from AMI to OMI, and predicting the distribution of immune cells, which provided a new perspective for improving myocardial fibrosis and adverse remodeling." (PMID 36561770, 2022).
oral cancer (1 paper, 2023). "Our results indicate that PFKFB2 expression is not significantly different between tumor-adjacent normal and tumor tissues in oral cancer patients." (PMID 37919747, 2023).
pancreatitis (1 paper, 2021). Inflammation of the pancreas. "This increase in severity of pancreatitis in Ins2Akita and PACIRKO mice was due to a loss of insulin-induced Akt-mediated phosphorylation of PFKFB2, which normally preserves glycolytic ATP supply to PMCA and prevents cytotoxic Ca2+ overload." (PMID 34282152, 2021). "Therefore, phosphorylation of PFKFB2 acts as a ‘volume control’ for glycolytic flux and thus ATP production and is thus likely to be the major molecular mechanism for the protective effects of insulin during pancreatitis." (PMID 34282152, 2021).
schizophrenia (1 paper, 2009). A major psychotic disorder characterized by abnormalities in the perception or expression of reality. "There is also evidence for linkage between enzymes that control glycolysis and schizophrenia, including PFKFB2, a rate limiting enzyme in glycolysis, and hexokinase, a regulatory enzyme in the metabolic pathway." (PMID 19772658, 2009).
skin tumor (1 paper, 2017). "During our previous skin carcinogenesis study using UCP2 KO mice, phosphorylated PFKFB2 was found to be upregulated in skin tumor tissues of the wild-type mice but not the UCP2 knockout mice, suggesting that UCP2 may positively regulate PFKFB2 expression." (PMID 29221144, 2017). "In this study, we identified that PFKFB2 was upregulated in skin tumor tissues of the wild-type mice but not in the UCP2 knockout mice, suggesting that PFKFB2 expression may be positively regulated by UCP2." (PMID 29221144, 2017).
thyroid cancer (1 paper, 2019). "PFKFB2 was also reported as a potential thyroid cancer diagnostic marker, being down-expressed in malignant compared to benign thyroid tissues." (PMID 30884810, 2019).
cancer (24 papers, 2015 to 2025). A tumor composed of atypical neoplastic, often pleomorphic cells that invade other tissues. "PFKFB1 encodes the isoforms that were originally identified in liver, muscle, and fetal tissues, while PFKFB2 encodes the isoforms present in the heart and kidney, and some cancer cells." (PMID 32717953, 2020). "The Akt/mTOR signaling pathway is typically abnormally activated in a variety of malignant tumors and causes abnormal expression of downstream genes such as PFKFB2, p21, Vimentin, and Bcl-2." (PMID 33282634, 2020). "The PFKFB1 gene encodes the isoforms that were originally identified in the liver, muscle and fetal tissue, while the PFKFB2 gene encodes the isoenzyme occurring in the heart and kidney and in some cancer cells." (PMID 30234009, 2018). "LINC00092 binds 6-phosphofructo-2-kinase/fructose-2,6-biphosphatase 2 (PFKFB2) and thus promotes malignant metastasis of OC by altering glycolysis and maintaining the local support function of cancer-associated fibroblasts (CAF)." (PMID 35431949, 2022). "Mechanistically, the SLIT2/ROBO1 axis exerted cancer-promoting effects on OS via activation of the SRC/ERK/c-MYC/PFKFB2 pathway." (PMID 29523788, 2018). "This cancer-promoting activity correlates with the Warburg effect through the activation of the SRC/ERK/c-MYC/PFKFB2 pathway." (PMID 29523788, 2018). "CAFs with high CXCL14 expression can increase the expression of long non-coding RNA LINC00092, which affects glycolysis by binding to 6-phosphofructo-2-kinase/fructose-2,6-bisphosphatase 2 (PFKFB2) and promoting cancer metastasis with the support of surrounding CAFs." (PMID 40136652, 2025). "Among this, a specific circRNA was found to regulate glycolysis in breast cancer cells via miR-1252-5p-mediated regulation of PFKFB2 (6-Phosphofructo-2-Kinase/Fructose-2,6-Biphosphatase 2) expression, emphasizing the metabolic reprogramming potential of EVs from cancer cells." (PMID 40806235, 2025). "Therefore, PFKFB2 has become a target of various miRNAs that mediate tumorigenesis in carcinoma cells." (PMID 37864733, 2023). "Small molecule inhibitors of PFKFB2-4 in combination with other drugs could increase the efficiency of cancer treatment." (PMID 30234009, 2018). "Since the alterations in cellular metabolism and the metabolic switch are relevant to many tumor cells, we believe that PFKFB2 could potentially be an interesting candidate in the association of tumorigenesis and metabolism in UCP2 highly expressed cancers." (PMID 29221144, 2017). "Since PFKFB2 is highly expressed in several cancers and its expression is positively correlated with carcinogenesis, we used siRNA interference to study whether inhibition of PFKFB2 reduces tumorigenicity of UCP2 overexpressed cells." (PMID 29221144, 2017). "Also, the PFKFB2-induced glycolytic cancer cell phenotype seems critical for the maintenance of CXCL14 secretion from CAFs, suggesting for LINC00092 a regulatory feedback loop between cancer cells and CAFs that is important for the maintenance of the tumor microenvironment." (PMID 31191327, 2019). "In fact, PFKFB2, PFKFB3, and PFKFB4 are overexpressed in the majority cancers, leading to a higher concentration of Fru-2,6-P2 and increased glycolytic flux to lactate." (PMID 29221144, 2017).
tumor (24 papers, 2010 to 2025). "Multivariate Cox regression analysis identified SNPs in 8 genes (Stx6, Ramp1, Traf3ip1, Nckap5, Pfkfb2, Trmt1l, Rprd1b, and Rer1) that were independently associated with age of tumour onset." (PMID 39067134, 2024). "We pooled all 20 genes (Stx6, Ramp1, Traf3ip1, Nckap5, Pfkfb2, Trmt1l, Rprd1b, Rer1, Sepsecs, Rhobtb1, Tsen15, Abcc3, Arid5b, Tnr, Dock2, Tti1, Fam81a, Oxr1, Plxna2 and Tbc1d31) together as the mouse tumour susceptibility gene signature (mTSGS)." (PMID 39067134, 2024). "Activation of RSK can be observed in BRAF V600E-mutated melanoma cells where phosphorylation of PFKFB2 promotes glycolytic flux and tumor growth." (PMID 33671514, 2021). "In summary, miR-489-3p can regulate each other with PFKFB2 in RB cells, and PFKFB2 is involved in tumor progression." (PMID 35184643, 2022). "Multivariate analyses flagged SNPs in 20 genes (Stx6, Ramp1, Traf3ip1, Nckap5, Pfkfb2, Trmt1l, Rprd1b, Rer1, Sepsecs, Rhobtb1, Tsen15, Abcc3, Arid5b, Tnr, Dock2, Tti1, Fam81a, Oxr1, Plxna2, and Tbc1d31) independently tied to various tumour characteristics, designated as a mTSGS." (PMID 39067134, 2024). "We hypothesized that LINC00115 promoted the RB cell proliferation, migration, and tumor growth by targeting the miR-489-3p/PFKFB2 axis." (PMID 35184643, 2022). "We hypothesized that LINC00115 promotes RB cell proliferation, migration, and tumor growth by targeting the miR-489-3p/PFKFB2 axis." (PMID 35184643, 2022). "Tumor cells generally increase glucose metabolism through glycolysis and pentose phosphate pathways to meet rapid cell proliferation’s bioenergy and biosynthesis requirements, and 6-phosphofructo-2-kinase (PFKFB2) is a key enzyme for glycolysis." (PMID 36387908, 2022). "Recent studies have also been revealed that PFKFB2 is overexpressed in a variety of tumors, although how the expression of this enzyme is mechanistically regulated during tumor progression remains unclear." (PMID 29523788, 2018). "Metabolic‐related genes such as PFKFB2 and ACOXL were upregulated in this group, underscores the paramount significance of sustaining metabolic stability in tumour biology." (PMID 40847563, 2025). "It has been mentioned previously that binding of PFKFB2 to LINC00092 maintains the glycolytic phenotype of OC cells and enhances tumor aggressiveness through interactions with CAFs that highly express CXCL14." (PMID 40045411, 2025). "Our data also demonstrate a potentially novel mechanism to understand UCP2's tumor-promoting role, which is through the AKT-dependent activation of PFKFB2 and thereby, the metabolic shift to glycolysis (the Warburg effect)." (PMID 29221144, 2017). "As expected, the same methylation pattern of PFKFB2, CXXC5 (tumor hypomethylation in relation to NT and BTL), and ATPV6V0C (tumor hypermethylation in comparison with NT and BTL) described in the microarray analysis and in the TCGA cross-study validation was confirmed." (PMID 30884810, 2019). "PFKFB2 and CXXC5 were hypomethylated in both tumor groups compared to NT and BTL." (PMID 30884810, 2019). "Upregulated genes such as ACSS1 (log2fc =0.50), PFKFB2 (log2fc = 0.57), GCK (log2fc =0.59), and PGAM2 (log2fc =0.59) indicate potential metabolic adaptations that may support tumour growth, though their impact is less pronounced compared to the WWOX/HIF1A ratio." (PMID 41007296, 2025). "Among most of these tumor types, a negative correlation between gene methylation and mRNA expression was revealed by calculating the Spearman correlation, including HIF1A, SLC16A1, UEVLD, SLC16A8, PFKFB2, LDHB, and SLC16A3." (PMID 37122693, 2023). "Given that PFKFB2 was activated in wild-type mice but not in UCP2 knockout mice during the skin carcinogenesis study, we speculated that UCP2 overexpression may bring a metabolic shift towards glycolysis by activating PFKFB2 as a potential novel mechanism of tumor promotion." (PMID 29221144, 2017).
PFKFB2 also shares sentences with these, for which no sentence is quoted: diabetic nephropathy (4 papers); Obesity (2); retinoblastoma (2); acute kidney injury (1); COVID-19 (1); hyperglycaemia (1); hyperlipidemia (1); kidney failure (1); leukemia (1); metabolic disorders (1); type 1 diabetes (1); ureteric obstruction (1).